STAT3 (signal transducer and activator of transcription 3)
Diseases named in the same sentence as STAT3 in open-access papers (continued):
Sharing a sentence is not in itself a finding about the gene and the disease.
pancreatic cancer (continued). "Using an HDAC3 inhibitor or knocking down HDAC3 weakens the binding of STAT3 to the PD-L1 promoter, thereby destroying the HDAC3/STAT3/PD-L1 signal transduction and improving the immunotherapy efficacy in pancreatic cancer." (PMID 38762484, 2024). "MiR-155 promotes (EMT), as well as regulates cancer cell invasion and migration, by modulating the STAT3 signaling pathway in pancreatic cancer cells." (PMID 38790924, 2024). "Overexpression and persistent activationof STAT3 is tightly relevant to the poor prognosis of pancreatic cancer.23−25 STAT3 is consistently activated in pancreatic cancer in multipleways." (PMID 38559310, 2024). "EF24 and 2d also suppressed phospho-STAT3 levels in pancreatic cancer cells, corroborating the docking results obtained for these two curcuminoids." (PMID 37514107, 2023). "The key role of STAT3 in promoting the progression of pancreatic cancer is well-established, but the way to inhibit STAT3 activity remains to be investigated." (PMID 37835536, 2023). "The influence of EF24 and 2d on phospho-STAT3 (p-STAT3) levels was investigated in MiaPaCa-2 and Panc-1 pancreatic cancer cells." (PMID 37514107, 2023). "Adiponectin can effectively inhibit proliferation and also induce apoptosis in pancreatic cancer cell lines indirectly by antagonizing leptin-induced signal transducer and activator of transcription 3 (STAT3) activation." (PMID 37444627, 2023). "PG-S3-001, a small molecule derivative of the SH-4-54 class of STAT3 inhibitors, was found to have an antiproliferative effect on pancreatic cancer cells both in vivo and in vitro." (PMID 36975494, 2023). "It was also seen that bromodomain inhibitors also downregulated protein levels of p-Erk 1/2 and p-STAT3 in mouse models of pancreatic cancer, thereby inhibiting the growth of cancer cells." (PMID 36975494, 2023). "Molecular targeting of the interleukin-6/glycoprotein-130/signal transducer and activator of transcription 3 signaling cascade is a promising approach in pancreatic cancer therapy." (PMID 36672405, 2023). "Rhein, a lipophilic anthraquinone, sensitizes pancreatic cancer cells to erlotinib by inhibiting STAT3." (PMID 36902166, 2023). "Western blot experiments verified that the phosphorylation level of STAT3 was upregulated in pancreatic cancer cells overexpressing IL20RB and was downregulated in those with IL20RB knockdown." (PMID 38098005, 2023). "It promotes the proliferation of human pancreatic cancer cells by expressing c-fos gene, Jun-B gene and cyclin E. Clinically, the content of LIF in quasi pancreatic cancer cell line Hs-700T is low, which can induce STAT3 phosphorylation." (PMID 36845384, 2023). "STAT3-silenced pancreatic tumors were characterized by the downregulation of the expression of STAT3-related genes such as MMP7, MMP9, and IL-1β." (PMID 38067351, 2023). "In another study, STAT3 activation correlated with dasatinib resistance in pancreatic cancer cells, while dual inhibition of STAT3 and SRC resulted in significantly smaller PDAC tumors in mice compared to monotherapy-treated groups." (PMID 37120696, 2023). "MyD88 hyperactivation causes NFkB activation and IL-6 secretion in CAFs, and IL-6 further triggers STAT3 signaling activation in pancreatic cancer." (PMID 38933287, 2023). "The combination of melatonin and sorafenib synergistically suppresses tumor growth in pancreatic cancer xenograft models through the downregulation of the PDGFR-β/STAT3 signaling pathway." (PMID 36979654, 2023). "Since high antiproliferative activities were observed for compounds 2c, 2d, and 2g–i, these active compounds were docked into STAT3, which is a reasonable target of curcumin and structurally related compounds in pancreatic cancer." (PMID 37514107, 2023). "Recent studies have shown that Raloxifene inhibits pancreatic cancer in vivo and in vitro via IL-6/gp130/STAT3 signaling." (PMID 37415745, 2023).
pancreatic cancer (continued). "IL22RA1 has been reported to promote the stemness and tumorigenicity of pancreatic cancer cells by activating STAT3." (PMID 38098005, 2023). "Panaxadiol has been found to inhibit the JAK2/STAT3 pathway, thus limiting the progression of pancreatic cancer." (PMID 37958803, 2023). "The inhibition of STAT3 activity has been shown to improve the survival prognosis of patients with prostate, colon, and pancreatic cancers." (PMID 36961170, 2023). "Alantolactone, a natural sesquiterpene lactone, also sensitizes pancreatic cancer cells to erlotinib and also to afatinib by inhibiting STAT3." (PMID 36902166, 2023). "Acetylation of CDK1 at K33 reduces pancreatic cancer stemness by inhibiting the phosphorylation of STAT3." (PMID 37743465, 2023). "CREB can activate the signal transducer and activator of STAT3 pathway for the tumorigenesis in pancreatic cancer." (PMID 37553583, 2023). "MLT has shown a synergistic anti-proliferative effect when combined with sorafenib, by dual suppression of the STAT3 pathway in pancreatic cancer cells in vitro and in vivo." (PMID 37371349, 2023). "Researchers have confirmed that interleukin-6 (IL-6) increased the activation of AR in pancreatic cancer cells by upregulating the phosphorylation of signal transducer and activator of transcription 3 (STAT3) and mitogen-activated protein kinase (MAPK)." (PMID 36834922, 2023). "Mechanistically, IL20RB enhances the stemness and chemoresistance of pancreatic cancer by promoting STAT3 phosphorylation, an effect that can be counteracted by a STAT3 phosphorylation inhibitors." (PMID 38098005, 2023). "Accordingly, dasatinib (SRC inhibitor) and erlotinib (EGFR inhibitor) treatment reduces pancreatic cancer cell migration and invasion, overcomes STAT3-mediated chemoresistance, and attenuates the growth of PDAC xenografts." (PMID 37120696, 2023). "Shikonin is found to be a potential inhibitor in pancreatic cancer as it mediates PD-L1 degradation which in turn suppresses immune evasion in pancreatic cancer cells via NF-κB/STAT3 and NF-κB/CSN5 signaling pathway." (PMID 36405061, 2022). "Curcumin was also shown to suppress STAT3-signaling pathways and inhibit the growth of several cancers including breast, prostate, and pancreatic cancers." (PMID 36299882, 2022). "Previous studies have provided evidence that the anticancer activity of naringenin and CPT occurs via inhibition of STAT3 signaling pathway in pancreatic cancer cells and vascular endothelial cells." (PMID 35606804, 2022). "We have previously shown that adiponectin inhibits pancreatic cancer by antagonizing leptin-induced STAT3 activation." (PMID 35121743, 2022). "According to previous research, rhein can sensitize human pancreatic cancer cells to EGFR inhibitors by inhibiting the STAT3 pathway." (PMID 36091816, 2022). "We suggest that Gadd45g restrains the interaction between myofibroblast PSCs and pancreatic cancer cells by weakening Stat3 activation during PanIN formation." (PMID 35211358, 2022). "All of these effects mediated by STAT-3 impact the overall survival of patients with gastric, hepatic and pancreatic cancer, osteosarcoma and PCa." (PMID 35703345, 2022). "Anti-CD147 antibody sensitized pancreatic cancer cells to gemcitabine and genfitinib by blocking CD44s-signal transducer and activator of transcription 3 signaling." (PMID 34974521, 2022). "STAT3 play a major role in many signaling pathways and have been proven to play a role in promoting pancreatic cancer progression." (PMID 35800364, 2022). "The inhibition of phosphorylation of STAT3 induces apoptosis in cultured pancreatic cancer cells and solid and hematological tumors." (PMID 35810312, 2022).
pancreatic cancer (continued). "Epithelial Stat3 ablation attenuated fibrosis and tumor progression in Smad4 mutant pancreatic tumors in mice, and several studies demonstrated that blockage of the IL-6/Stat3 axis suppresses Kras-induced pancreatic adenocarcinoma." (PMID 35211358, 2022). "Relevant studies have shown that REG3A acts as a growth-promoting cell regulator and interacts with JAK2/STAT3 signaling to form a positive feedback loop to accelerate pancreatic cancer cell growth under IL-6-related inflammatory conditions." (PMID 36105933, 2022). "LDL-C can promote the proliferation of pancreatic cancer cells by activating the STAT3 pathway and upregulating the levels of oncogenes such as Bcl-2, Bcl-xL, survivin controlled by this transcription factor in pancreatic cancer cells." (PMID 35251975, 2022). "In conclusion, our study identified the mechanism by which TST-induced ferroptosis in pancreatic cancer cells through STAT3/GPX4 signalling." (PMID 35859150, 2022). "Silence of STAT3 by siRNA blocked STAT3 activation and inhibited the mesenchymal phenotype of pancreatic cancer cells." (PMID 35251963, 2022). "Pancreatic cancer cells also express a variety of factors including VEGF to activate Stat3 and Akt, and subsequently modulate macrophage behavior." (PMID 35453676, 2022). "In vitro, STAT3 inhibitor STX-0119 showed cytotoxicity to a variety of pancreatic cancer cell lines, which showed weak PD-L1 expression." (PMID 36291659, 2022). "Research DirectionsUSP5 enhances STAT3 signaling in cancer cells and promotes migration and invasion of pancreatic cancer." (PMID 36291659, 2022). "REG3B/G are C-type secreted lectins that play active roles in pancreatitis and in the transition from pancreatitis to pancreatic cancer through different mechanisms, including induction of STAT3, RAF-MEK-ERK signaling, and immune cell modulation." (PMID 36316305, 2022). "IL-6 also induces a mesenchymal phenotype in human pancreatic cancer cells via STAT3 activation and SNAI1 induction." (PMID 36010693, 2022). "Mechanistically, circCUL2 functioned as a ceRNA and modulated the miR-203a-3p/MyD88/NF-κB/IL6 axis, thereby further activating the STAT3 signaling pathway in pancreatic cancer cells to induce PDAC progression." (PMID 35189958, 2022). "circCUL2- induced iCAFs contributed to the tumorigenesis and metastasis of PDAC through increased secretion of IL6 and further activation of the STAT3 signaling pathway in pancreatic cancer cells." (PMID 35189958, 2022). "Recently, supernatant derived from activated PSC-conditioned medium was shown to stimulate Stat3 activation in pancreatic cancer cells, leading to the accumulation of ECM proteins and exacerbation of tumorigenesis and drug resistance." (PMID 35211358, 2022). "Gp130/STAT3 pathway regulates the TGF-β expression in cancer stem cells such as cells in pancreatic cancer, thereby enhancing the function of TGF-β/Smad pathway in EMT." (PMID 36291659, 2022). "This has also been demonstrated with LysM-Cre–mediated STAT3 deletion which reduced tumor growth in pancreatic tumor models and improved T cell-mediated anti-tumor responses observed in models of lung and colorectal tumors." (PMID 35053592, 2022). "The same intervention was then used to observe the proliferation of the three cell lines, and STAT3 overexpression also partially reversed the effect of TST on killing pancreatic cancer cells." (PMID 35859150, 2022). "STAT3 is over-activated in pancreatic cancer and inhibitors targeting STAT3 have anti-tumor effects and also reverse the immune escape mechanism in TME." (PMID 36291659, 2022). "The activation of STAT3 in PDAC has been reported in patient-derived clinical specimens and pancreatic cancer cells and is a prognostic risk factor." (PMID 36010693, 2022). "Recent work shows that STAT3 is an Sp-regulated gene in pancreatic cancer cells that can be targeted by BITC and other ROS inducers, establishing a potential therapeutic strategy for targeting STAT3." (PMID 35684331, 2022).
pancreatic cancer (continued). "MDC-1112 reduces the accumulation of mitochondrial STAT3 and induces apoptosis in pancreatic cancer cells." (PMID 34976224, 2022). "The study of STAT3 function and the use of STAT3 inhibitors will also lead to the study of the mechanism of pancreatic cancer and the development of drugs toward the path of precision medicine, thus prolonging the survival of patients." (PMID 36291659, 2022). "With regard to pancreatic cancer, we demonstrated that the effects of adiponectin and AdipoRon on cancer cells were partially due to suppression of the STAT3 signaling pathway as well as AMPK-pathway activation resulting in decreased proliferation." (PMID 35121743, 2022). "The authors concluded that the STAT3 regimen improves the efficacy of anti-MEK agents in resistant pancreatic cancers." (PMID 36145523, 2022). "Mechanistically, circFARP enhances leukemia inhibitory factor (LIF) expression by decoying miR-660-3p, and LIF secreted from CAFs induces gemcitabine resistance in pancreatic cancer cells by activating the LIF/STAT3 pathway." (PMID 36467402, 2022). "circCUL2 functioned as a ceRNA and modulated the miR-203a-3p/MyD88/NF-κb/IL6 axis, inducing the conversion of NFs into iCAFs, thereby further activating the STAT3 signaling pathway in pancreatic cancer cells to induce the progression of PDAC." (PMID 35189958, 2022). "Mechanistically, circCUL2 functioned as a ceRNA and modulated the miR-203a-3p/MyD88/NF-κB/IL6 axis, thereby further activating the STAT3 signaling pathway in pancreatic cancer cells to induce the progression of PDAC." (PMID 35189958, 2022). "Human pancreatic cancer cells were shown to utilize IL‐6‐mediated Jak2‐STAT3 signaling to form a trimeric complex of Cdc42 with its interaction partner IQGAP1 and STAT3 for IQGAP‐mediated activation of Cdc42." (PMID 33960104, 2022). "circPTPN22 is upregulated in pancreatic cancer, and it interacts directly with STAT3 to block the interaction between STAT3 and SIRT1." (PMID 36467402, 2022). "Meanwhile, miR-1181 suppresses the proliferative and invasive behavior of pancreatic cancer cells by inhibiting the expression of signal transducer and activator of transcription 3 (STAT3)." (PMID 36292753, 2022). "For example, phosphorylated STAT3 can upregulate KLF4 level to maintain stemness of pancreatic cancer cells." (PMID 35027543, 2022). "Although pancreatic cancer cells were used in both experiments, the phosphorylation site played an important role in the localization of p-STAT3 in mitochondria." (PMID 35559037, 2022). "They found that the apoptosis induced in pancreatic cancer cells was through the inhibition of STAT3 signaling." (PMID 36428575, 2022). "In pancreatic cancer, STAT3 activation has also been correlated with developing resistance to MEK inhibitors." (PMID 36145523, 2022). "Secreted by CAFs in the microenvironment, LIF was shown to bind on the surface of pancreatic cancer cells, induce STAT3 phosphorylation, and ultimately stimulate PDAC growth and progression." (PMID 33630157, 2021). "Consistently, overexpression of SAA and activation of STAT3 were observed in the liver of pancreatic cancer and colorectal cancer liver metastasis patients." (PMID 34067719, 2021). "REG3A has been described as a proliferating factor following liver and skin injuries as well as a driver of pancreatic cancer cell growth through JAK2/STAT3 signaling pathways in response to interleukin-616,18." (PMID 34099862, 2021). "This is further evidence in support of dual targeting of STAT3 and Ref‐1 and the deleterious effects that this combination has on pancreatic cancer cells." (PMID 33274592, 2021). "Among these, Napabucasin, a STAT3 inhibitor approved for the treatment of metastatic colorectal carcinoma and pancreatic cancer, is an example." (PMID 34381714, 2021).
pancreatic cancer (continued). "Specifically, the stimulation of TLR4 and CAP1 receptors with Resistin, a hormone released by macrophages in the cancer microenvironment, activates the STAT3 pathway that confers to pancreatic cancer cells the ability to resist cancer therapy." (PMID 34884547, 2021). "Inhibition of circRNA_100782 suppressed cell proliferation and colony formation through downregulation of IL6R and STAT3, which are oncogenes in pancreatic cancer." (PMID 34439315, 2021). "For example, anoikis-resistant pancreatic cancer cells exhibited significantly increased expression and activation of STAT3." (PMID 33440835, 2021). "We previously demonstrated that dual targeting of Ref‐1 and STAT3 is synergistic and decreases cell viability in pancreatic cancer cells." (PMID 33274592, 2021). "Through targeting STAT3, miRNA-130b is regarded as a prognostic marker to suppress proliferation and induce apoptosis of pancreatic cancer cells." (PMID 34867344, 2021). "Resistin combines with CAP1 and TLR4 to promote the proliferation, migration and invasion of pancreatic cancer cells through the STAT3 signaling pathway." (PMID 34485124, 2021). "Numerous studies have shown that STAT3 is an effective drug target for the treatment of pancreatic cancer." (PMID 33420372, 2021). "Four JAK and seven STAT family members have been described in humans, although significant elevations in expression and activation of JAK1/2 and STAT3, in particular, have been observed in pancreatic cancer patients." (PMID 33546207, 2021). "In pancreatic cancer, IL-22 promoted pancreatic cancer stemness via IL22RA1/STAT3 signalling, establishing the mechanism of regulation of cancer stemness in the tumour microenvironment." (PMID 34572431, 2021). "Leptin upregulates the expression of matrix metalloproteinase-13 (MMP-13) through the JAK2/STAT3 signaling pathway and enhances the invasion ability of pancreatic cancer cells." (PMID 34485124, 2021). "N4 selectively inactivated STAT3 activation, thereby suppressing the growth and migration of pancreatic cancer cells in vitro." (PMID 33420372, 2021). "In conclusion, fraxetin enhances the anti-tumor activity of gemcitabine and suppresses pancreatic cancer development by antagonizing STAT3 activation." (PMID 34320467, 2021). "STAT3 governs an early event that is acinar-to-ductal metaplasia during pathogenesis of pancreatic cancer." (PMID 34535145, 2021). "A comprehensive meta-analysis reported that the overexpression of STAT3 was correlated with low disease-free survival and poor prognosis of the stomach, lung, brain, liver, bone, prostate, and pancreas cancers." (PMID 34867344, 2021). "Luteolin inhibit pancreatic cancer cell invasion by inhibiting STAT3 signaling and secretion of EMT and MMP." (PMID 34539403, 2021). "Napabucasin (BBI608) is a small molecule inhibitor of STAT3 evaluated for the treatment of several cancers including platinum-resistant ovarian cancer, gastric adenocarcinoma, and pancreatic cancer." (PMID 33546207, 2021). "Pancreatic liver metastasis represents a significant therapeutic challenge and evidence had been provided that STAT3 is involved in key steps of pancreatic cancer liver metastasis, including metastatic niche formation and tumor growth." (PMID 33420372, 2021). "N4 also selectively inhibited STAT3 activation in pancreatic cancer cells, while displayed little impact on STAT1 and STAT5, which shared the most conserved structure features to STAT3 among STAT members." (PMID 33420372, 2021). "In pancreatic cancer, Stat3 plays a pivotal role in oncogenic transformation, cell survival, proliferation and resistance to apoptosis." (PMID 33637083, 2021). "The results of the orthotopic animal model showed that pterostilbene combined with chloroquine significantly inhibited pancreatic cancer growth, delayed tumor quadrupling times, and inhibited autophagy and STAT3 in pancreatic tumors." (PMID 34771150, 2021).